FGF19 (fibroblast growth factor 19)
Diseases named in the same sentence as FGF19 in open-access papers (continued):
Sharing a sentence is not in itself a finding about the gene and the disease.
hepatocellular carcinoma (continued). "In addition, FGFR4 may be constitutively-activated or overexpressed in a variety of human neoplasias, including hepatocellular carcinoma, prostate cancer, rhabdomyosarcoma and breast cancer, and the potential utility of FGF19 and/or FGFR4 as a target for growth inhibition has been proposed." (PMID 21203561, 2010). "Furthermore, a positive feedback loop involving FGF19, HOXB5, and FGFR4 has been identified in hepatocellular carcinoma, further amplifying oncogenic signaling." (PMID 41584352, 2026). "Moreover, an antibody blocking the interaction of FGF19 to FGFR4 limited the formation of colon tumor xenografts in vivo, preventing hepatocellular carcinomas in FGF19 transgenic mice." (PMID 37108717, 2023). "Since FGF21 or other endocrine FGF such as FGF19 can affect tumor growth, we hypothesized that FGF21 produced by Atg7-knockout (KO) hepatocytes may affect the behavior of Atg7-KO hepatoma in an autocrine manner." (PMID 35321438, 2022). "Because chronic FGF19 overexpression was shown to induce hepatocellular carcinoma in mice by activating STAT3 signaling, a nontumorigenic FGF19 analogue (NGM282, also known as M70 and aldafermin) that does not activate STAT3 was developed." (PMID 35415765, 2022). "This study helps to elucidate a relationship between FGF19 and its respective receptor FGFR4 in the promotion of hepatic stem cells as indicated by increased EpCAM within the carcinogenesis sequence of fatty liver to hepatocellular carcinoma in the specimens." (PMID 27447573, 2016). "Clearly FGF19 expression is significantly higher in hepatocellular carcinoma compared to non-malignant liver and has oncogenic activity." (PMID 28943626, 2015). "To date, the binding of human FXR in primary human hepatocytes (PHHs) or hepatoma cell lines has been characterized to limited genes, including ABCB4 (ATP-binding cassette, sub-family B, member 4), ABCB11, FGF19 (fibroblast growth factor 19), ICAM1 (intercellular adhesion molecule 1), and NR0B2." (PMID 25198545, 2014). "Moreover, we examined the expression and the distribution of FGF19 and FGFR4 in 5 hepatocellular carcinoma cell lines (HepG2, HuH7, HLE, HLF, and JHH7) using RT-PCR and immunohistochemistry." (PMID 22309595, 2012). "The FGF19/FGFR4 signaling pathway dysregulation is widely detected in many types of diseases including cancers, especially in hepatocellular carcinoma (HCC)." (PMID 34576070, 2021). "FGF19 is however, also a strong inducer of liver carcinomas in mice and it is of high importance to mitigate the mitogenic, FGFR4-mediated effect of FGF19 to allow human therapy, even though species difference may indicate that FGF19 is less mitogenic in human cellular systems." (PMID 33414764, 2020). "For example, inhibition of FGF19 in CCND1-amplified tumors (11q13 amplification) using anti-FGF19 antibodies has been shown to be an effective therapy for hepatocellular carcinoma (HCC), and the blockage of its FGFR receptors has shown promising clinical results in FGF19/FGF4+ HCC." (PMID 36980521, 2023). "There is growing evidence that the FGFR4 pathway may contribute to the development of hepatocellular carcinoma (HCC), and selective FGFR4 inhibitors have shown remarkable anti-tumor activity in HCC xenografts harboring FGF19-overexpression." (PMID 28445152, 2017). "Although fibroblast growth factor 19 (FGF19) can promote liver carcinogenesis in mice, its involvement in human hepatocellular carcinoma (HCC) has not been well investigated." (PMID 22309595, 2012). "Indeed, FGF19 expressing transgenic mice exhibit increased hepatic BrdU incorporation and elevated expression of α-fetoprotein (AFP) mRNA, a marker for hepatocyte proliferation, as early as 2 months of age, and go on to spontaneously develop hepatocellular carcinomas." (PMID 21437243, 2011).
hepatocellular carcinoma (continued). "In hepatocellular carcinoma (HCC), the expression level of FGF19 in HCC tissues was significantly higher compared with noncancerous liver tissues and tumor FGF19 mRNA expression was an independent prognostic factor for mortality." (PMID 29731962, 2018).
Obesity (80 papers, 2011 to 2026). Accumulation of substantial excess body fat. "In patients with both obesity and type 2 diabetes, these two common metabolic disorders share some pathophysiology, which was associated with decreased fasting plasma levels of FGF19." (PMID 41522208, 2026). "Fasted serum FGF-19 levels are reduced in individuals with overweight, obesity, and NAFLD and it has even been suggested as a diagnostic biomarker for NASH." (PMID 38892505, 2024). "A recent study has shown that FGF19 can promote osteogenic differentiation and prevent bone loss caused by obesity." (PMID 37454120, 2023). "Administering FGF19 into a liver-specific Klb-deficient mouse with diet-induced obesity can still significantly reduce body weight accompanied with lower food intake, reduced serum plasma concentration, and hepatic triglyceride levels." (PMID 35682726, 2022). "Most recently it was shown that circulating FGF19 is associated with remission of diabetes after Roux-en-Y gastric bypass surgery for obesity." (PMID 24176017, 2013). "We show that FGF19-7 is equally efficacious as wild type FGF19 in regulating glucose, lipid, and energy metabolism in both diet-induced obesity and leptin-deficient mouse models." (PMID 22457778, 2012). "They concluded that FGF19 alleviates obesity-induced bone loss in mice." (PMID 41185883, 2025). "By binding to the intestinal FXR, bile acids can induce the expression of endocrine hormone fibroblast growth factor 19 (FGF19), which suppresses lipogenesis and increases fatty acid oxidation in the liver, thereby regulating body weight gain and reducing the risk of obesity." (PMID 37512553, 2023). "Obesity is an important factor associated with the FGF 19 levels." (PMID 31181641, 2019). "Obesity showed an association between decreased FGF19 levels and NAFLD." (PMID 31181641, 2019). "Weight loss may diminish obesity risk via regulation of adipose-tissue-derived factors, finally modulating concentrations of FGFs (FGF19, FGF21) and β-klotho co-receptor." (PMID 31151464, 2019). "Interestingly, the “leptin-like” actions of central FGF19, still operative in leptin-deficient mice, would be useful to manage obesity and its associated defects." (PMID 24567901, 2014). "Transgenic overexpression of FGF19 in mice elevated circulating FGF19 levels and subsequently reduced high-fat diet-induced weight gain, increased metabolic rate and improved obesity-associated metabolic defects, including insulin resistance, liver steatosis and plasma lipid levels." (PMID 23922646, 2013). "Studies have indicated that circulating FGF19 levels are significantly reduced in obese patients and markedly increase after bariatric surgery, suggesting that FGF19 may be a target through which weight loss surgery improves obesity." (PMID 41114583, 2025). "Thus, we preliminarily identified whether the beneficial effects of FGF19 on obesity were partially associated with mediating the biological functions of adipose tissues, especially BAT." (PMID 33751819, 2021). "Our study adds valuable insights to the existing body of literature on the relationship between FGF19, obesity, and diabetes in the Chinese population." (PMID 41522208, 2026). "Various studies demonstrate the possibility of using FGF19 for the treatment of diabetes and obesity." (PMID 41394119, 2025). "FGF19 ameliorates obesity-induced skeletal muscle atrophy, regulates skeletal muscle mass, and mitigates skeletal muscle wasting potentially." (PMID 40801027, 2025). "Individuals with T2D and obesity after RYGB presented with increased serum FGF-19 levels (p = 0.024) and decreased total bile acid (p = 0.01) and FGF-21 levels (p = 0.005)." (PMID 41155711, 2025). "For example, FGF19 possesses potent pharmacological benefits in administration against obesity, diabetes, and fatty liver disease." (PMID 41394119, 2025).
Obesity (continued). "In severe obesity, excessive adiposity alters this gut-liver axis, potentially disrupting hepatocyte-mediated regulation of FGF19, an enterokine produced in the ileum in response to bile acid signaling." (PMID 40943431, 2025). "In individuals with metabolic syndrome or obesity, circulating FGF19 levels are reduced, whereas CYP7A1 expression and total bile acid pool size are increased in type 2 diabetes, suggesting disruption of the negative FXR/FGF19 feedback loop." (PMID 41465592, 2025). "Patients with severe obesity had significantly lower circulating FGF19 levels than controls, which inversely correlated with body size measurements." (PMID 40943431, 2025). "We found decreased plasma FGF19 levels in patients with severe obesity, consistent with downregulation of the farnesoid X receptor (FXR) in the gut, a key regulator of FGF19 expression." (PMID 40943431, 2025). "In contrast, FGF-19 transgenic mice exhibited increased metabolic rate and resistance to diet-induced obesity." (PMID 40943671, 2025). "Post hoc analysis with Bonferroni correction further demonstrated significantly lower FGF-19 concentrations in diabetic patients with overweight (p < 0.01) and obesity (p < 0.001) compared to those with a normal BMI." (PMID 40943671, 2025). "FGF-19 is reduced in diabetes and obesity and is inversely correlated to BMI shown in patients going through bariatric surgery." (PMID 41272580, 2025). "Several reports have shown that circulating FGF19 levels are lower in individuals with obesity and MASLD supporting the role of FGF19 as a hormone in metabolism." (PMID 38587078, 2024). "We observed an increased postprandial response of FGF19 after surgery, especially in patients with T2D at surgery, which is in line with previous findings that FGF19 is reduced in patients with obesity and that the levels are restored after bariatric surgery." (PMID 39096744, 2024). "We found that circulating levels of FGF19 were reduced in individuals with obesity and comorbidities, such as type 2 diabetes and metabolic dysfunction–associated fatty liver disease." (PMID 38587078, 2024). "We provide evidence that the FXR/FGF19 pathway is activated following bariatric surgery of patients with obesity." (PMID 39096744, 2024). "FGF19 can act against obesity-induced muscle atrophy, metabolic derangement, and abnormal irisin secretion by promoting PGC-1α and FNDC5 expression." (PMID 37266540, 2023). "For example, the presented data of treatment with FGF-21 agonists or FGF-19 antibodies or analogues showed the great potential for their use in metabolic diseases, such as obesity, through beneficial effects on IS, lipid levels or food intake." (PMID 37239098, 2023). "Sleeve gastrectomy surgery increased FGF-19 right after surgery, slowly corrected obesity-related inflammation, and improved adipocytokine secretion." (PMID 38116338, 2023). "FGF19 reverts obesity-induced muscle atrophy and restores irisin levels, thus playing a role in improving skeletal muscle health." (PMID 38201893, 2023). "On the contrary, body weight loss and increased energy expenditure prevailed in transgenic mice expressing human FGF-19 and these mice furthermore presented a resistance to obesity and insulin desensitization." (PMID 37239098, 2023). "Decreased circulating FGF19 levels have been reported in patients with obesity and insulin-resistance." (PMID 35663311, 2022). "Both clinical and animal studies have demonstrated an inverted relationship between blood FGF-19 and obesity." (PMID 36362225, 2022). "FGF 19 has a close connection with obesity and correlates negatively with BMI in obese patients with DM." (PMID 35277004, 2022). "FGF19 suppressed hepatic lipogenesis and increases hepatic fatty acid oxidation, thereby reducing body weight gain from diet-induced obesity." (PMID 35495722, 2022).
Obesity (continued). "FGF19 can also ameliorate sarcopenia and skeletal muscle atrophy induced by glucocorticoid treatment or obesity, suggesting that FGF19 and its analogs has potential therapeutic application for these symptoms." (PMID 35682726, 2022). "In all cases the tissue Rb, similarly to other measured obesity-related markers, inversely correlated with FGF-19." (PMID 36362225, 2022). "To investigate the therapeutic effect of FGF19 on obesity and SO, we examined body weight, lean muscle mass, grip strength and biological parameters in young and old HFD‐fed mice." (PMID 33751819, 2021). "In this study, we mainly investigated the protein degradation pathway of ubiquitinated protease to indicate the protective effect of FGF19 on obesity‐induced muscle atrophy." (PMID 33751819, 2021). "Modified forms of FGF19 have been created that have been effective in reducing body weight, plasma glucose and triglyceride levels in diet induced obesity." (PMID 35116006, 2021). "A recent study has shown that administration of FGF19 causes skeletal muscle hypertrophy, by stimulating the phosphorylation of ERK1/2 and P70S6K1, and ameliorates obesity-induced skeletal muscle atrophy in mice." (PMID 34491915, 2021). "Opposite to plasma FGF21, fasted serum FGF19 levels are reduced in individuals with overweight, obesity and NAFLD." (PMID 33414764, 2020). "Administration of human recombinant FGF19 to mice in which obesity was induced by high-fat diet resulted in a dose-dependent significant decrease in body weight and blood glucose concentration." (PMID 30927227, 2019). "We also found that the FL-I group had lower FGF 19 levels, lower body weight, and lower waist circumferences among the patients with obesity and T2DM before surgery." (PMID 31181641, 2019). "After bariatric surgery, the FGF 19 level significantly increased in subjects with obesity and subjects with obesity and DM." (PMID 31181641, 2019). "The levels of FGF 19 in patients with obesity (BMI, range of 25–34.9 kg/m2) and morbid obesity (BMI, 35–66 kg/m2) were 151.8 pg/mL and 118.2 pg/mL, respectively." (PMID 31181641, 2019). "The levels of FGF 19 have a negative correlation with BMI and patients with morbid obesity have lower FGF 19 levels than patients with obesity." (PMID 31181641, 2019). "Many animal studies have confirmed the therapeutic potential of FGF19 in the treatment of metabolic disorders, such as obesity or diabetes." (PMID 30927227, 2019). "This view was confirmed in a finding that subjects with obesity and DM had lower serum levels of FGF 19 and higher levels of bile acid clinically, which is consistent with the results of our current study." (PMID 31181641, 2019). "The effects of central FGF19 are mainly studied in animal models for obesity and diabetics, because overexpression of FGF19 in mice resulted in increased energy expenditure and animals on a high fat diet (HFD) did not become diabetic or obese." (PMID 29163019, 2017). "Overall, our work unveils novel regulatory pathways induced by FGF19 that will be useful in the design of novel strategies to control diabetes in obesity." (PMID 24567901, 2014). "Fibroblast growth factor (FGF) 19 is a hormone-like enterokine released postprandially that emerged as a potential therapeutic agent for metabolic disorders, including diabetes and obesity." (PMID 24567901, 2014). "The post-prandial enterokine FGF19 has been shown to alter carbohydrates metabolism in mouse models of obesity and diabetes." (PMID 24567901, 2014). "A beneficial role of these polypeptides in metabolic signaling is suggested by the higher energy expenditure, reduced adiposity, and resistance to diet-induced obesity of FGF19 transgenic mice." (PMID 24176017, 2013). "Experimental administrations of FGF19 and transgenic FGF19 mice have shown decreased liver fat content, improved hepatic and serum lipid profiles, and resistance to high-fat diet-induced obesity." (PMID 24165751, 2013).
Obesity (continued). "FGF21 and FGF19 are potent regulators of glucose, lipid and energy metabolic homeostasis and suppress obesity and diabetes through targeting adipose tissue and liver." (PMID 24279986, 2013). "In an effort to compare efficacy of the factors in another model of obesity we examined the effects of chronic FGF19 and FGF21 infusion in ob/ob mice." (PMID 22675463, 2012). "Previously, therapeutic potential for FGF19 in the treatment of obesity and diabetes has been proposed; however, its promotion of hepatocyte proliferation and carcinogenic potential challenges the development of FGF19 for chronic use." (PMID 21437243, 2011). "Our findings demonstrate significant alterations in circulating levels of FGF19, FGF21, leptin, irisin, and adiponectin, providing evidence that severe obesity is associated with dysregulated organokine networks that contribute to liver disease development and progression." (PMID 40943431, 2025). "However, this marked efficacy was accompanied with increased bile duct proliferation and increased inflammation, cautioning the safety of the combination of FGF19 and PPARα activation in the treatment of obesity and MASLD." (PMID 40815899, 2025). "Circulating FGF19 levels decrease in human participants with obesity and comorbidities." (PMID 38587078, 2024). "Our study showed that patients with obesity have decreased FGF19 levels." (PMID 38587078, 2024). "In addition to enhancing skeletal muscle quality and function, FGF19 also safeguards against obesity-induced muscle atrophy and steatosis." (PMID 38902808, 2024). "Reduced levels of FGF-19 are observed in obesity and related disorders, including NAFLD." (PMID 38892505, 2024). "Consistent with previous work, our data show that postprandial FGF19 concentration is lower in individuals with obesity, without a strong association with postprandial blood glucose levels." (PMID 38587078, 2024). "Interestingly, decreased fasting FGF-19 levels, reflecting impaired intestinal or hepatic FXR signalling, have also been associated with obesity and the development of metabolic-associated fatty liver disease (MAFLD)." (PMID 35745254, 2022). "In addition, FGF-19 transgenic mice were resistant to HFD-induced obesity and increased fat accumulation." (PMID 36362225, 2022). "These metabolic observations suggest that FGF19 may be a potential candidate for treatment of obesity." (PMID 35116006, 2021). "We further hypothesized that FGF19 had protective effects against obesity‐induced muscle atrophy via the AMPK/SIRT‐1/PGC‐1 signalling pathway." (PMID 33751819, 2021). "However, FGF19 improved lipid/ glucose metabolic disturbance in skeletal muscle and even the whole body, suggesting its therapeutic role in obesity and SO." (PMID 33751819, 2021). "Indeed, inhibition of PPAR-α expression is reported to abolish the protective effects of human fibroblast growth factor 19 (FGF19) on obesity-induced sarcopenia." (PMID 34356299, 2021). "Interestingly, FGF19 levels were negatively correlated with fasting plasma glucose and shown to be decreased in impaired fasting glucose, obesity, T2D, and NAFLD subjects." (PMID 33101202, 2020). "The discovery of endocrine fibroblast growth factors (FGF), including FGF-21 and FGF-19, has uncovered new mechanisms that regulate metabolism and lipid homeostasis, and has provided potential therapeutic targets for type 2 diabetes, obesity, and hepatic steatosis." (PMID 32069846, 2020). "Some evidence has also shown an impaired FGF19 and 21 biosyntheses in obesity." (PMID 31151464, 2019). "Moreover, the total bile acid levels significantly decreased and FGF 19 levels significantly increased in the patients with obesity and T2DM 1 year after SG." (PMID 31181641, 2019). "Low FGF19 concentrations have been reported in metabolic syndrome, obesity and type 2 diabetes." (PMID 29866129, 2018). "However, the contributions of FGF19 (or FGF15 in mouse) to obesity and metabolic dysfunctions remain to be clarified." (PMID 24567901, 2014).